CXCL12 (C-X-C motif chemokine ligand 12)
Diseases named in the same sentence as CXCL12 in open-access papers (continued):
Sharing a sentence is not in itself a finding about the gene and the disease.
cancer (continued). "It plays an important role, in addition to chemotaxis, in cell survival, cellular proliferation, and metastatic spread of cancer cells that express CXCL12, leading to the formation of secondary colonies, and a particular role in HIV infection has also been discovered." (PMID 33092204, 2020). "CXCL12/CXCR4 signaling represents an important delivery target for cancer cells." (PMID 33233846, 2020). "Therefore, the blocking of the CXCR4/CXCL12 axis is an important approach in order to inhibit cancer metastasis in therapy." (PMID 32486408, 2020). "Indeed, it is known that the osteotropism of CXCR4 + cancer stem cells depends on their ability to follow the CXCL12 gradient towards the bone marrow." (PMID 33238004, 2020). "Thus, our data also suggest a response that compromises inflammatory response through the mir-140/Cxcl12 axis in muscle wasting during cancer cachexia." (PMID 31013615, 2019). "Notably, 10 over-expressed genes (Comp, Mmp3, Adipoq, Angptl7, Fgg, Hp, Mstn, Saa1, Serpina3n, and Cxcl12) are translated into secreted proteins, and therefore, can be further explored as potential cancer cachexia biomarkers." (PMID 31013615, 2019). "Moreover, SDF-1/CXCL12 can also induce cancer cell proliferation via a PI3K/Akt and MAPK signalling-dependent mechanism." (PMID 31861782, 2019). "Second, CXCR4-overexpressing cancer cells can then migrate along CXCL12 gradients." (PMID 31810195, 2019). "In conclusion, we identified new microRNA–mRNA interactions, such as miR-27a/Foxo1, miR-27a/Mef2c, miR-27b/Cxcl12, miR-27b/Mef2c, miR-140/Cxcl12, miR-199a/Cav1, and miR-199a/Junb, that may contribute to muscle wasting in cancer cachexia." (PMID 31013615, 2019). "Furthermore, CXCL12 or stromal cell-derived factor 1 is considered one of the most significant chemokines to promote drug resistance in various cancers." (PMID 31395078, 2019). "We further predicted new microRNA–mRNA interactions, such as miR-27a/Foxo1, miR-27a/Mef2c, miR-27b/Cxcl12, miR-27b/Mef2c, miR-140/Cxcl12, miR-199a/Cav1, and miR-199a/Junb, which may contribute to muscle wasting in cancer cachexia." (PMID 31013615, 2019). "Specifically, our results suggest that microRNA/mRNA interactions miR-27a/Foxo1, miR-27a/Mef2c, miR-27b/Cxcl12, miR-27b/Mef2c, miR-140/Cxcl12, miR-199a/Cav1, and miR-199a/Junb may contribute to muscle wasting in cancer cachexia." (PMID 31013615, 2019). "Recently, it was reported that T cells may be excluded from cancer cell nests by high CXCL12 levels." (PMID 30813533, 2019). "CXCR4 is the cognate receptor for SDF-1/CXCL12 and is also implicated in cancer metastasis." (PMID 31861782, 2019). "In addition, Cxcl12, a stromal cell–derived α chemokine member known to be an important regulator of quiescence in stem and cancer cells, was upregulated after radiation and chemotherapy." (PMID 31292293, 2019). "CXCL12 activates the CXCR4 receptor that is overexpressed in several human cancer cells." (PMID 31332163, 2019). "However, the novel involvement of CXCR7 as a high affinity‐binding partner of CXCL12 begs for reconsideration of the whole CXCR4 paradigm in the context of cancer biology." (PMID 29460395, 2018). "Furthermore, this axis has also been recognized as a prognostic marker in several tumors and preclinical models; signifying that metastasis is mediated by CXCR4 activation and migration of cancer cells towards CXCL12 expressing organs." (PMID 30383826, 2018). "Among different types of cancers, the dimeric form of CXCL12 can produce opposite effects." (PMID 29977203, 2018). "Moreover, AHSG shows synergy with traditional chemotactic as SDF-1/CXCL12 to mediate chemotaxis and invasion of cancer cells through the extracellular matrix." (PMID 30075788, 2018).
cancer (continued). "Doing a differential expression between the two clusters of cancer fibroblasts, we found metastatic fibroblasts were found to express higher levels of soluble factors compared to primary fibroblasts including, CXCL12, S100A6, S100A10, SFRP2,SFRP4,IGF1, CXCL14, ANGPTL4 and IL6." (PMID 30383866, 2018). "Interestingly, CXCL12 is also expressed by cancer cells in TME and, in coordination with CXCR4, regulates the migration of the cancer cells for metastasis." (PMID 30220913, 2018). "Beyond these, CXCL12 may be highly induced under certain pathological conditions including ischemia, inflammation, hypoxia, cancer, and autoimmune diseases." (PMID 29977203, 2018). "Such substantially disparate CXCL12 values could point to distinct functions for CXCL12 in different malignancies and pathologies, as well as additive/synergistic roles for other cytokines in promoting cancer phenotypes." (PMID 29596520, 2018). "Understanding the generation of CXCL12 gradients is crucial to inhibiting cancer metastasis." (PMID 29117251, 2017). "It has been reported that differential expression of CXCL12 occurrs in numerous cancers." (PMID 28272462, 2017). "MiR-125b was a critical mediator of CXCL12/CXCR4 axis in cancer EMT." (PMID 28176874, 2017). "We hypothesized that miRNAs might be critical downstream mediators of CXCL12/CXCR4 axis involved in cancer invasion and chemoresistance in CRC." (PMID 28176874, 2017). "Blocking CXCR4 and/or CXCL16 neutralization, alone or in combination, resulted in significant inhibition of patient-derived cancer cells migration to brain metastatic CAF aggregates, further supporting the importance of CXCL16 and CXCL12 in migration of CTCs into brain-associated microenvironment." (PMID 28649646, 2017). "The angiogenic actions mediated by the CXCL12/CXCR4 transduction pathway in cancer may involve the activation of EPCs, as well as the recruitment of additional pro-angiogenic molecules such as VEGF." (PMID 29240722, 2017). "In previous computational and experimental studies, we found that a CXCL12 gradient on the order of 0.002 nM/μm, which corresponds to a difference of 10–20 molecules across the cell diameter, may be large enough to drive cancer cell migration." (PMID 29117251, 2017). "We further analysed CXCL12/CXCR4 signalling in cancer progression." (PMID 28489070, 2017). "Acquirement of migratory functionality might play an important role in the development of metastasis: high expression of CXCR4 on cancer cells might induce their migration to tissue with high levels of CXCL12." (PMID 28356064, 2017). "Furthermore, CXCL12 knockdown by application of two different shCXCL12 or the CXCR4 antagonist AMD3100 decreased the survival of cancer cells." (PMID 28489070, 2017). "In this study, we hypothesized that miRNAs might be an important mediator in the progression of cancer, such as invasion, metastasis and chemoresistance, in response to the activation of CXCL12/CXCR4 axis." (PMID 28176874, 2017). "Bone marrow adipocytes also secrete several pro-inflammatory mediators such as IL-1B, IL-6, leptin, adiponectin, vascular cell adhesion molecule 1 (VCAM-1), tumor necrosis factor alpha (TNF-alpha) and CXCL12 that increase bone tropism, proliferation, and survival of certain cancer cells." (PMID 28800754, 2017). "However, the underlying mechanisms of CXCL12/CXCR4 axis and cancer progression have been poorly explored." (PMID 28176874, 2017). "Interestingly, CQ and HCQ can induce CXCR4 internalisation in cancer stem cells, making these cells less sensitive to CXCL12 signals." (PMID 29225688, 2017). "In addition, silencing of CXCR4, a rhodopsin-like G-protein-coupled receptor that selectively binds CXCL12 chemokine, by miR-520h has been shown to successfully block invasion and metastasis of cancer cells." (PMID 28182660, 2017). "CXCR4 and its ligand, CXCL12, can promote metastasis by preventing anoikis in cancer cells." (PMID 28489070, 2017).
cancer (continued). "Previously, we calculated that cancer cells respond to CXCL12 gradients as small as 0.002 nM/μm; circadian fluctuations might cause gradients to fall above and below this value throughout the course of a day." (PMID 29117251, 2017). "In fact, circadian fluctuations may influence the dosing schedule of cancer therapeutics, especially those that target the CXCL12 gradient or signaling axis." (PMID 29117251, 2017). "CXCL12 gradient dynamics remain unclear, and yet understanding these gradients in vivo is crucial to grasping the mechanism that drives cancer cells along the metastatic cascade." (PMID 29117251, 2017). "These human carcinomas migrated more across ihLEC than hLEC to either S1P or CXCL12." (PMID 28487567, 2017). "Previous reports suggested that the CXCR4/CXCL12 signaling-mediated chemotaxis may be involved in migration of CXCR4+ cancer cells towards an increasing gradient of CXCL12 across vascular wall." (PMID 26993780, 2016). "Previous studies have indicated that cancer associated fibroblasts (CAF) stimulates cancer cell motility or invasion by producing soluble factors such as Hepatocyte growth factor (HGF), Transforming growth factor (TGF)-β, CXCL12." (PMID 27136922, 2016). "Other authors also indicated that high CXCL12 levels may be related with a tendency to metastasis of cancer cells, while the low CXCL12 expression exists in the site of primary EC." (PMID 27041792, 2016). "Thus, we propose that high CXCR4 on the cell surface, combined with decreased intracellular regulatory GRK3, leads to impaired receptor internalization and more active CXCL12-mediated migration of the cancer cell." (PMID 27049755, 2016). "Much remains to be unraveled about CXCL12-related mechanisms of intercommunication damage that may favor growth of cancer cells at the expense of healthy hematopoiesis during biological contingencies such as hematological malignancies and biological stress." (PMID 27594840, 2016). "Some authors have investigated polymorphisms of CXCL12 in disease pathogenesis, including cancer, but its value as a susceptibility marker is not well determined." (PMID 27830498, 2016). "The CXCR4/CXCL12 axis can coordinate metastasis of a variety of cancers." (PMID 25888626, 2015). "CXCL12 signaling through CXCR4 also plays critical roles in cancer metastasis." (PMID 25773070, 2015). "The axis of CXCL12/CXCR4 has been considered to play an important role for cancer cell migration." (PMID 26078947, 2015). "Metastasis and growth of many cancers is driven by CXCL12 through CXCR4 and may be modulated by DPPIV-mediated CXCL12 degradation." (PMID 26552750, 2015). "We thought the stably CXCL12 transfection can change the behavioral biology of cancer cells." (PMID 24810923, 2014). "In support of this notion, we demonstrated for the first time, to our knowledge, that the CXCL12 neutralizing antibody can alleviate established cancer pain hypersensitivity by i.t. administration, despite that the effect of anti-hyperalgesia and anti-allodynia is transient." (PMID 24735601, 2014). "Certainly, our western blot result showed that CXCL12 upregulation started from day 3 after TCI, while the cancer pain hypersensitivity was undetectable until day 5, suggesting that spinal CXCL12 may be a trigger mediator for development of BCP." (PMID 24735601, 2014). "Further, CXCL12 is a chemoattractant for lymphangiogenic endothelial cells (LECs), inducing the migration and tubule formation of LECs in vitro and lymphangiogenesis in vivo and correlating with lymphatic vessel density in cancer tissues." (PMID 25165728, 2014). "Thus, CXCL12 appears to be broadly effective in limiting cancer progression, invasion, and metastasis and this benefit resultsfrom cell-type specific mechanisms." (PMID 24594697, 2014).
cancer (continued). "CXCR4, a cell surface chemokine receptor, binds and responds to cytokines of the CXC chemokine family such as a CXCL12 (or SDF-1), and it has a wide cellular distribution including lymphocytes, hematopoietic stem cells, endothelial and epithelial cells, and cancer cells." (PMID 24829804, 2014). "Moreover, CXCR4-positive cancer cells can migrate toward distant organs in response to CXCL12 gradient." (PMID 25471741, 2014). "This is maybe because cancers types differ by carcinogenic mechanisms and environmental exposures and have disparate responses to CXCL12 G801A genotypes." (PMID 25268356, 2014). "CXCR4 and its ligand CXCL12 can promote the proliferation, survival, and invasion of cancer cells." (PMID 24810923, 2014). "The interaction of GBM cells with the microenvironment that protects cancer cells from the chemo- and radio-therapy stress, becomes even more relevant in the context of CXCL12/CXCR4 up-regulation observed after treatment with anticancer drugs, and particularly after anti-VEGF antibodies." (PMID 24904289, 2014). "In agreement with the results of the present study, overexpression of CXCR4 in GBMs has been recognized as an attribute of cells with progenitor/stem properties and CXCL12 promotes specifically the proliferation of these cells compared to more differentiated cancer cells." (PMID 24662753, 2014). "An important member of the CXC chemokine subfamily, CXCL12 has been widely explored in cancer." (PMID 23322021, 2013). "Interestingly, in undifferentiated cells, genes involved in cancer/inflammatory pathways such as CXCL12, IGFBP3, IL1B, and WNT5A were down-regulated by PCB-153, whereas they were up-regulated by AhR ligands." (PMID 22262711, 2012). "Together, these studies and data presented herein demonstrate an important role for DIP-directed mDia2-dependent F-actin dynamics in regulating morphological plasticity in motile cancer cells, and reveal a novel role for CXCL12 in inducing amoeboid transitions within 3D matrices." (PMID 23024796, 2012). "In this way, CXCL12 mediates the cancer cell proliferation action of oestrogen and may account for the poor prognosis of patients with high CXCL12." (PMID 22415233, 2012). "A more complete understanding of CXCL12/CXCR4 signaling pathways may support efforts to develop therapeutics for cancer." (PMID 23202899, 2012). "Notably, cancer cells usually express functional receptors for CXCL12 and some cancers constitutively express CXCL12." (PMID 22529914, 2012). "Although these data may suggest divergent functions for CXCR4 and CXCR7 in cancer cells, little is known regarding the frequency of co-expression and therein the mechanism for propagation of CXCL12 signals." (PMID 22472349, 2012). "In addition, the CXCR4/CXCL12-axis has been shown to play a pivotal role in trafficking and homing of normal stem cells and metastasis of cancer stem cells to organs that express high levels of CXCL12, such as the lymph nodes, lungs, liver, and bone." (PMID 22485156, 2012). "In ovarian cancer, cancer cells produce CXCL12 and VEGF in response to hypoxia." (PMID 23109879, 2012). "As we have previously shown in a cohort of 183 patients, CXCL12 immunoreactivity in cancer cells was heterogeneous, with scores of 0 (undetectable production) obtained in 16 patients and of 5 to 7 (strong immunoreactivity) obtained in eight patients in our cohort of 54 patients." (PMID 21750716, 2011). "Moreover, CXCL12 regulates the homeostasis, angiogenesis, proliferation, survival and migration of cancer cells." (PMID 21695171, 2011). "Indeed, a lower proportion of basal-like cancers expressed CXCL12 (59%) compared with luminal cancers (74%)." (PMID 21521526, 2011). "In conclusion, our results provide evidence that CXCR4 is up-regulated in CRC and stimulation of CXCR4 bearing cancer cells with CXCL12 led to increased migration, an effect which could be inhibited both by CXCR4 siRNA and neutralizing CXCR4 antibodies." (PMID 21349176, 2011).
cancer (continued). "Thus, novel agents that can downregulate the CXCR4/CXCL12 axis have therapeutic potential in inhibiting cancer metastasis." (PMID 21880153, 2011). "Epithelial cells in benign, borderline and malignant tumors also expressed CXCL12." (PMID 21410972, 2011). "In addition, 49 genes have been reported to be relevant to immune diseases, such as CXCL12, COL1A1, MMP9, and CD36, likely reflecting an inflammatory–type response often associated with cancer." (PMID 21060876, 2010). "However, as a potent chemotactic factor for leukocytes, CXCL12 also has the potential to enhance anti-cancer immunity." (PMID 20849618, 2010). "We have also documented a specific pathway of activation in cancer cells (CXCL12/HB-EGF-stimulated cancer cell release of GM-CSF) that may match the specific biological properties of mononuclear phagocytes." (PMID 20946648, 2010). "In addition, we found that CXCL12 induced a significant and dose-dependent increase of cancer cell invasion through Matrigel." (PMID 20380740, 2010). "Furthermore, CXCR7 as a inclassical chemokine receptor plays an important role in the CXCL12/CXCR4-mediated transendothelial migration (TEM) of human cancer cells." (PMID 20380740, 2010). "In addition, when HeLa and DLD-1 cancer cells were stimulated with 200 ng/mL CXCL12 and/or 25 ng/mL HB-EGF, GM-CSF proteins were detected by immunocytochemistry after 24 hours and new GM-CSF transcripts (as assessed by RT-PCR) appeared after 2 hours." (PMID 20946648, 2010). "A tissue with high expression of CXCL12 (for example, liver or bone marrow) may represent a site that preferentially attracts both macrophages and cancer cells, which co-migrate depending on their expression of the CXCL12 receptors CXCR4 and/or CXCR7." (PMID 20946648, 2010). "It will also be important to investigate whether CXCL12 isdownregulated by phytochemicals in tissues that serve as preferred sites of metastasisfor these cancers, such as the lung and bone." (PMID 19325924, 2009). "Furthermore, since many other phytochemicalshave been implicated in cancer protection, it will be prudent to determinewhether phytochemicals other than DIM and genistein exert similar effects on CXCR4and CXCL12 levels." (PMID 19325924, 2009). "Although the CXCL12/CXCR4 and CXCL12/CXCR7 axes are important factors in cancer cell survival, differences exist between their roles in cancer, and whether they function independently or synergistically should be determined." (PMID 19352387, 2009). "Importantly, when signalling through CXCR4, CXCL12 stimulates intracellular calcium-flux and chemotaxis in lymphocytes, leukocytes and a range of cancer cells including breast." (PMID 17726466, 2007). "DPP-4 inhibition may elevate CXCL12 levels, potentially promoting metastasis in these cancers." (PMID 40282969, 2025). "Also, breast CAF‐secreted CXCL12 was shown to promote the growth of xenograft tumors formed by patient‐derived CAFs and cancer cells and osteopontin‐activated fibroblast‐derived CXCL12 was proposed to play a role in inducing epithelial‐mesenchymal‐transition and angiogenesis using in vitro assays." (PMID 39887653, 2025). "The non-response to immunotherapy may be linked to CXCL12 in cancer cells in some pancreatic and CRCs with specific characteristics (microsatellite stable)." (PMID 39070795, 2024). "Elevated CXCL12 levels may be related to a tendency of cancer cells to metastasize because it has been shown that an upregulation of CXCL12 and its specific receptor levels is associated with an increase in the advanced stages of OC, which might be a result of cancer’s ability to spread." (PMID 38673838, 2024). "Thus, the authors sought to evaluate whether inhibiting CXCL12 action increases cancer cell sensitivity to PD-1 blockade." (PMID 38106674, 2023). "Finally, post-translational modifications of CXCL12 can influence cancer progression." (PMID 36725964, 2023). "CXCL12 could rapidly up-regulate PDL1 of cancer cells in a short time." (PMID 38001512, 2023).